GLS2 (glutaminase 2)
Diseases named in the same sentence as GLS2 in open-access papers (continued):
Sharing a sentence is not in itself a finding about the gene and the disease.
diabetes (3 papers, 2012 to 2023). "In line with previous reports, our findings suggested that GLS2 downregulation caused by diabetes could inhibit ATP production in podocytes." (PMID 37057309, 2023). "In conclusion, GLS2 impairment in pancreatic β-cells induces insulin impairment and paradoxical glucagon increase, resulting in diabetes mellitus." (PMID 37147373, 2023). "Here, we identified a novel role of LRH‐1 in alleviating diabetes‐induced podocyte injury via enhancing glutaminases 2 (GLS2)‐dependent Gln mobilization and utilization in mitochondria." (PMID 37057309, 2023). "LRH‐1 activation modulates diabetes‐induced podocyte injury by restoring GLS2‐derived glutaminolysis." (PMID 37057309, 2023). "Furthermore, Gls2 CKO exhibited significant diabetes mellitus with gluconeogenesis and insulin resistance when fed a high-fat diet." (PMID 37147373, 2023). "Impairment of glutamine degradation and utilization in podocytes under diabetic kidney disease: LRH‐1 positively regulates GlS2‐mediated glutaminolysis, and downregulation of LRH‐1 expression contributes to diabetes‐induced disturbance of energy metabolism and injury in podocytes." (PMID 37057309, 2023).
malignant glioma (3 papers, 2017 to 2023). A grade III or grade IV glioma arising from the central nervous system. "In the cytoplasm, glutamine is converted to glutamate by glutaminase isoenzymes 1 and 2 (GLS1 and GLS2), and in malignant gliomas, GLS2 has been reported to be downregulated while GLS1 is expressed." (PMID 37626776, 2023).
atherosclerosis (2 papers, 2024 to 2025). A disease characterized by the build-up of fatty material and calcium deposition in the arterial wall resulting in partial or complete occlusion of the arterial lumen. "In addition, GLS isoform 2 (GLS2) enzyme was upregulated in the multipotent progenitor population (MPP) in patients with coronary artery disease (CAD) compared to patients without atherosclerosis." (PMID 40577101, 2025).
bacteremia (2 papers, 2018 to 2025). "The fact that GLS2 mutation is associated with complicated bacteremia could thus be the consequence of increased NO levels in these patients, resulting in the production of excessive cytotoxic oxygen radicals." (PMID 30289878, 2018). "Existing gene expression studies in individuals with bacteremia showed that GLS2 expression was lower in SAB cases compared to controls, and this pattern was reproduced in mouse RAW 264.7 cells." (PMID 30289878, 2018).
brain cancer (2 papers, 2021). A primary or metastatic malignant neoplasm affecting the brain. "The precise biological role of each GLS isoforms (KGA and GAC) and GLS2 gene in brain cancer is not completely understood." (PMID 33681764, 2021). "By contrast, overexpression of GLS2 acts in an anti-oncogenic manner in liver and brain cancer." (PMID 34332338, 2021).
Cirrhosis (2 papers, 2014 to 2017). A chronic disorder of the liver in which liver tissue becomes scarred and is partially replaced by regenerative nodules and fibrotic tissue resulting in loss of liver function. "In this study, we found that the GLS2 protein expression was significantly decreased in majority of primary HCCs that we examined compared with non-tumor liver tissues, including liver tissues with cirrhosis and hepatitis." (PMID 24797434, 2014).
epilepsy (2 papers, 2024 to 2025). A brain disorder characterized by episodes of abnormally increased neuronal discharge resulting in transient episodes of sensory or motor neurological dysfunction, or psychic dysfunction. "Second, further studies have shown that overexpression of GLS2 during the latent period of epilepsy reduces susceptibility to chronic epilepsy, reduces epileptic activity according to behavioral tests, and reduces abnormal discharges in LFP recordings." (PMID 39404053, 2024). "Specifically, the regulation of GLS2 mainly reverses mitophagy during the latent period of epilepsy by affecting the expression of PINK1, p62, LC3, and TOMM20, thereby reducing the occurrence of SLEs." (PMID 39404053, 2024). "After the satisfactory confirmation of GLS2 overexpression, a model of KA‐induced epilepsy was developed." (PMID 39404053, 2024). "First, compared to that in the control group, the expression of GLS2 in mice with KA‐induced epilepsy was lower on the seventh day." (PMID 39404053, 2024). "Subsequently, we demonstrated that GLS2 interacts with mitophagy‐related proteins in a KA‐induced epilepsy mouse model." (PMID 39404053, 2024). "Such coordination might have consequences on the epilepsy occurrence, where Gls2 is down-regulated (as we also found)." (PMID 40699779, 2025). "We hypothesize that GLS2 influences epilepsy by participating in mitophagy processes through the critical role that autophagy plays in epilepsy and its vital role in autophagy." (PMID 39404053, 2024). "As a result, the goal of this study was to investigate the expression patterns of GLS2 in epilepsy and to determine whether GLS2 regulates epileptic‐like alterations in kainic acid (KA)‐induced epilepsy mouse models via the protective mechanism of mitophagy." (PMID 39404053, 2024). "In conclusion, we initially discovered that GLS2 is downregulated in the glutamate‐induced neuronal excitatory injury mode, and in the hippocampus in a latent epilepsy mouse model, revealing a hitherto unknown and critical role of GLS2 in epilepsy." (PMID 39404053, 2024). "Thus, GLS2 might control seizures, and our findings provide a fresh avenue for antiepileptic treatment and offer novel insights into treating and preventing epilepsy." (PMID 39404053, 2024). "These morphological results indicate that mitophagy is delayed by overexpression of GLS2, which inhibits the formation of autophagosomes in hippocampal CA1 neurons during the latent period of epilepsy." (PMID 39404053, 2024). "Third, although GLS2 is a GLS, we did not detect the metabolic levels of glutamine or glutamic acid in epilepsy." (PMID 39404053, 2024).
esophageal cancer (2 papers, 2025 to 2026). A primary or metastatic malignant neoplasm involving the esophagus. "Metastasis is a leading cause of mortality in esophageal cancer, and recent research has identified glutaminase 2 (GLS2) as a critical enzyme involved in glutamine metabolism." (PMID 41517663, 2026).
head and neck cancer (2 papers, 2019 to 2025). A primary or metastatic malignant neoplasm affecting the head and neck. "In this regard, and considering previous reports on head and neck cancer cells, it may be hypothesized that the effect of GLS2 on the PI3K/AKT pathway may be related to our finding linking GLS2 and PDH activity downregulation." (PMID 39796278, 2025).
lupus (2 papers, 2022 to 2025). "Some studies have demonstrated that GLS2 protein expression is downregulated in CD4+ T cells from lupus-prone MRL/lpr mice and SLE patients." (PMID 39388708, 2025). "Moreover, overexpression of GLS2 corrected ROS levels and restored IL-2 production by lupus CD4+ T cells." (PMID 36211442, 2022). "In lupus-prone mice and SLE patients, GLS2 expression is reduced in CD4+ T cells, and GLS2 reduces ROS levels and promotes the ability of CD4+ T cells to produce IL-2 by demethylating the IL-2 gene." (PMID 36211442, 2022).
myocardial infarction (2 papers, 2022 to 2023). Gross necrosis of the myocardium, as a result of interruption of the blood supply to the area, as in coronary thrombosis. "MiR-190a-5p reduces lipid peroxidation by inhibiting GLS2 mRNA, thereby inhibiting ferroptosis and lowering the risk of myocardial infarction." (PMID 36310600, 2022).
thyroid cancer (2 papers, 2023). "To elucidate the mechanism of STAG2-deficient thyroid cancer cells being more sensitive to glutamine deprivation, we first determined the impact of STAG2 knockdown on the expression of glutamine transporter SLC1A5 and glutaminases GLS and GLS2, which are essential for glutamine metabolism." (PMID 37479689, 2023). "Mechanistically, knocking down STAG2 in BRAF-mutant thyroid cancer cells decreases the protein stability of c-Myc via the ERK/AKT/GSK3β feedback pathway, thereby impairing glutamine metabolism of thyroid cancer cells by down-regulating its downstream targets such as SCL1A5, GLS and GLS2." (PMID 37479689, 2023).
adenoma (1 paper, 2024). A neoplasm arising from the epithelium. "Several enzymes involved in NEAA biosynthesis were significantly regulated (highlighted in bold) in late-stage adenocarcinoma cells (M) in comparison to early adenoma cells (C1), such as upregulation of GPT and GLS2, and downregulation of GOT2 and GPT2." (PMID 39332495, 2024).
astrocytomas (1 paper, 2021). "The GLS2 expression level was significantly lower in astrocytoma than NN, with the lowest expression in GBM of MS subtype in our cohort." (PMID 33910646, 2021). "Expression analysis of transcript coding for the key enzymes involved in glutaminolysis, GLSiso1, GLSiso2, GLS2, GLUD1, GOT1, GOT2, and GPT2 was performed in our series of astrocytomas of different malignant grades and NN brain samples." (PMID 33910646, 2021).
E. coli (1 paper, 2018). "We found that GLS2 expression was significantly suppressed in S. aureus and E. coli BSI patients relative to healthy controls, and that the significant difference in was present in both white and African-American subsets." (PMID 30289878, 2018). "Having shown that GLS2 expression is suppressed in patients with S. aureus or E. coli BSI and in RAW 264.7 macrophages challenged with S. aureus, we next sought to understand the significance of the observed GLS2 expression pattern." (PMID 30289878, 2018).
fungi infection (1 paper, 2023). "Finally, we detected the glutamine metabolism enzymes GLS, GLS2, and GLUL mRNA expression under fungi infection in murine CD4+ T cells and CD4+ T cells obtained from CD and UC patients." (PMID 37124046, 2023).
glaucoma (1 paper, 2022). Increased pressure in the eyeball due to obstruction of the outflow of aqueous humor. "In human LC cells from glaucoma patients, there was a significant upregulation of glutaminase-2, an enzyme that converts glutamine to glutamate." (PMID 35992925, 2022).
hearing loss (1 paper, 2025). "Investigating the role of Gls2 with targeted inhibitors could provide deeper insights into metabolic flexibility in cochlear dysfunction and hearing loss." (PMID 41007265, 2025).
Insulin resistance (1 paper, 2023). Increased resistance towards insulin, that is, diminished effectiveness of insulin in reducing blood glucose levels. "The reduction in blood glucose levels or percentage after insulin loading was significantly lower for Gls2 CKO mice than for RIP-Cre mice, showing insulin resistance." (PMID 37147373, 2023).
lactic acidosis (1 paper, 2013). Metabolic acidosis characterized by the accumulation of lactate in the body. "Both acidosis and lactic acidosis induced GLS2 mRNA and protein levels while repressing the level of GS protein." (PMID 24359630, 2013).
liver diseases (1 paper, 2015). "We compared the expression of GLS1 and GLS2 in a large set of clinical samples including HCC, normal liver, and other liver diseases." (PMID 25844758, 2015). "Staining for GLS2 was positive in 37.5% of HCC samples (5/112 were strongly stained and 37/112 were weakly stained) and 80% or 100% in other liver diseases and normal liver tissue." (PMID 25844758, 2015). "In a serial of human liver diseases that mimic the progression of HCC transformation, i.e., from normal liver, to fibrotic liver, to dysplastic nodule, to HCC, we found increased GLS1 expression at each step, while GLS2 was significantly down-regulated in HCC." (PMID 25844758, 2015).
lung squamous cell carcinoma (1 paper, 2021). "GLS2 knockdown was shown to inhibit cell proliferation by down-regulating the mTORC1 signaling and inducing autophagy in Gln-dependent lung squamous cell carcinoma cell lines." (PMID 33619235, 2021).
myeloma (1 paper, 2024). "In certain cancers, GLS2 functions in a manner contrary to its role as a tumor suppressor; however, in specific myeloma cell lines, increased expression has been noted." (PMID 39050886, 2024). "This elevation may serve as an adaptive mechanism to metabolic stress, allowing myeloma cells to optimize their energy and nutrient acquisition through improved Gln metabolism; thereby, GLS2 gene also supports the proliferation and survival of myeloma cell lines." (PMID 39050886, 2024). "Collectively, these findings suggested that Gln and GLS1, but not GLS2, support myeloma cell progression." (PMID 39050886, 2024). "Given that GLS2 expression was not elevated in myeloma samples, GLS2 may act as a tumor suppressor in this context." (PMID 39050886, 2024).
Seizure (1 paper, 2024). A seizure is an intermittent abnormality of nervous system physiology characterized by a transient occurrence of signs and/or symptoms due to abnormal excessive or synchronous neuronal activity in the brain. "Seizures are less likely to occur when GLS2 expression is upregulated in the CA1 area of the hippocampus." (PMID 39404053, 2024). "Western blot analysis and statistical analysis revealed that, compared with the control group, the GLS2 expression in the Seizure group was substantially lower." (PMID 39404053, 2024).
skin cancer (1 paper, 2019). "For GLS2, high expression resulted in poor survival in patients with colon, blood, ovarian, and thymoma cancer, and high survival in patients with brain, kidney, and skin cancer." (PMID 30871151, 2019).
squamous cell carcinoma (1 paper, 2019). A carcinoma arising from squamous epithelial cells. "Adenocarcinomas showed higher expression of SLC1A5 and GLS2 in both protein (P = 0.08 and P = 0.019, respectively) and mRNA level (P < 0.001 and P = 0.003, respectively), compared to squamous cell carcinomas." (PMID 31668020, 2019).
thymoma (1 paper, 2019). A neoplasm arising from the epithelial cells of the thymus. "GLS was frequently over-expressed in breast, esophagus, head-and-neck, and blood cancers, and was associated with a poor prognosis, whereas GLS2 overexpression implied poor overall survival in colon, blood, ovarian, and thymoma cancers." (PMID 30871151, 2019).
type 2 diabetes (1 paper, 2023). "However, the expression of the GLS2 gene in β-cells was significantly increased in type 2 diabetes donors compared to nondiabetic donors but not in other non-β-cells." (PMID 37147373, 2023).
virus infection (1 paper, 2024). "In HCT8 cells, GLS protein expression was modestly increased (1.7-fold) with virus infection, whereas GLS2 protein levels were not changed." (PMID 39662828, 2024).
tumor (136 papers, 2012 to 2025). "The liver-type glutaminase (encoded by GLS2) can exhibit dualistic effects on tumorigenesis depending on tumor type." (PMID 40710547, 2025). "GLS2 is a critical regulatory factor for glutamine cleavage and is associated with tumor inhibitory activity." (PMID 39404053, 2024). "In a very recent study, Suzuki and colleagues not only confirmed the tumor-suppressive activity of GLS2 in HCC, but also shed new light on the mechanism underlying this phenomenon." (PMID 38067269, 2023). "The precise mechanism underlying the tumor-suppressing function of GLS2 is yet to be fully elucidated, but it is believed to involve the regulation of cellular metabolism and redox balance." (PMID 38067269, 2023). "Among these is GLUD1, which was weakly associated with GLS and GLS2 at both mRNA and protein levels in the low and high proliferative tumours." (PMID 34439127, 2021). "High GLS and GLS2 mRNA were associated with lower tumour grade (p = 0.017, p = 0.026, respectively)." (PMID 34439127, 2021). "GLS2 copy number gain was associated with cluster 1, which are predominantly luminal B tumours (p = 0.000006)." (PMID 34439127, 2021). "GLS and GLS2 are respectively indirect and direct downstream targets of c-Myc35 and were significantly overexpressed in FH-deficient tumor specimens." (PMID 31804603, 2019). "GLS-encoded glutaminase promotes tumorigenesis, while GLS2-encoded glutaminase displays tumor-suppressive properties." (PMID 30669455, 2019). "GLS1 is upregulated in cells with increased rates of proliferation, and accounts for the majority of glutaminase activity in some human tumor cells; whereas, GLS2 expression is associated with resting or quiescent cell states." (PMID 25844758, 2015). "Furthermore, we present the context-dependent oncogenic and tumor-suppressor properties of GLS2, and delve into the mechanisms underlying these phenomena." (PMID 38067269, 2023). "In addition, High GLS2 protein expression was associated with luminal B compared to luminal A tumours in DCIS." (PMID 34439127, 2021). "Our current work further suggests a causative link between GLS2 expression and tumor suppression." (PMID 32042057, 2020). "GLS2 exhibits a distinctly divergent expression pattern in comparison to GLS1, which functions as an environmentally dependent tumour suppressor gene and is associated with a favourable prognosis." (PMID 40598593, 2025). "Elevated asparagine metabolism is associated with an immunosuppressive tumor microenvironment, marked by increased Alanine/Serine/Cysteine Transporter 2 (ASCT2) and decreased Glutaminase 2 (GLS2) expression." (PMID 40868256, 2025). "Nevertheless, evidence has emerged demonstrating that GLS2 is overexpressed in certain tumours, thereby contributing to their development." (PMID 40598593, 2025).